MYC (MYC proto-oncogene, bHLH transcription factor)
Diseases named in the same sentence as MYC in open-access papers (continued):
Sharing a sentence is not in itself a finding about the gene and the disease.
neuroblastoma (continued). "Interestingly, a ChIP-chip array study of MYCN/c-MYC target genes in neuroblastoma demonstrated that distinct MYCN/c-MYC target gene expression was associated with overall survival, and independent of well-established markers such as MYCN amplification, disease stage, and age at diagnosis." (PMID 23226679, 2012). "Neuroblastoma, another childhood cancer with origins in fetal development, can also be driven by a super‐enhancer translocation into the MYC locus." (PMID 39887412, 2026). "High-risk neuroblastoma is characterized by MYCN amplification and high MYCN or MYC gene expression." (PMID 41940329, 2026). "Applying TSProm to human brain, liver, and testis promoters, we identified clinically relevant transcription factors (TFs) in the brain, including SP1, MYC, and HES6, whose associations with gliomas and neuroblastomas highlight clinical relevance." (PMID 42244857, 2026). "Real-time PCR analysis showed that c-MYC knockdown resulted in a significant (p < 0.01) decrease in PA2G4 mRNA expression compared to the control after 48 h in neuroblastoma cells, suggesting that c-MYC plays a role in PA2G4 transcriptional regulation." (PMID 41002386, 2025). "Mycn, a member of the Myc/MYC oncogene family, is recognized for its roles in embryonic development and cancer, notably aggressive neuroblastoma and triple-negative breast cancer." (PMID 40862719, 2025). "By combining MYC inhibition with small molecule treatments, we induce an immunogenic response in neuroblastoma cells, making them more recognizable and attackable by immune cells." (PMID 40552293, 2025). "Consistent with the neuroblastoma data, medulloblastoma cell lines with elevated MYC expression were significantly more responsive to MP1." (PMID 41149606, 2025). "Previous studies have shown that WS6 is effective in MYCN-driven neuroblastoma models; however, its activity in other MYC-driven cancers remains to be determined." (PMID 41002386, 2025). "While the PA2G4-MYCN interaction in neuroblastoma has been well characterized, little is known about its potential role in regulating c-MYC." (PMID 41002386, 2025). "The oncogenic driver neuroblastoma-derived MYC (MYCN) exacerbates ER stress by increasing calcium ion efflux from the ER into mitochondria, promoting glycolytic and oxidative stress." (PMID 41198652, 2025). "Our process involves co-culturing autologous PBMCs with irradiated neuroblastoma cells that have been treated with MYC inhibitors." (PMID 40552293, 2025). "To address the unmet clinical need for high-risk neuroblastoma therapy, we recently identified a therapeutic target, RBM39, a MYC target that regulates pre-mRNA splicing and appears to be essential to neuroblastoma survival." (PMID 40962798, 2025). "To further elucidate the changes by which MYC suppression effects human neuroblastoma tumor cells, we conducted a comparative analysis using NanoString Human Cancer Signaling 360 Profiling." (PMID 40552293, 2025). "Dysregulation of MYC, such as amplification of MYCN, is associated with tumorigenesis, especially for neuroblastoma." (PMID 39802403, 2025). "MYC family is composed of three closely related genes, MYC (encoding Cellular-MYC), MYCN (encoding Neural-MYC), and MYCL (encoding Lung-MYC), identified in epithelial cells, neuroblastoma, and small cell lung cancer, respectively." (PMID 40362259, 2025). "MYC regulates polyamine biosynthesis in several cancers, including leukemia, lung cancer, neuroblastoma, and breast cancer." (PMID 40444051, 2025). "BET bromodomain inhibition via JQ1 and related inhibitors show promising effects in preclinical models of MYC-driven neuroblastoma, glioblastoma and medulloblastoma." (PMID 40075567, 2025).
neuroblastoma (continued). "The aurora kinase A inhibitors MLN8054 and MLN8327 unsettled the MYC-Aurora kinase A complex, leading to N-MYC destabilization and tumor deterioration in N-MYC amplified neuroblastoma." (PMID 39779613, 2025). "We refer to these three neuroblastoma-specific programs as “Adrenergic I (sympathoblast-like)”, “Adrenergic II (pre-neuronal-like)”, and “Neuroblastoma-MYC” (NB-MYC)." (PMID 38898465, 2024). "CUDC-907, a dual PI3K and HDAC inhibitor, has been shown to suppress the growth of MYC-driven neuroblastoma and medulloblastoma and to exhibit radiosensitizing properties in DMG models by inhibiting radiation-induced DDR pathways." (PMID 39766049, 2024). "DLST (dihydrolipoamide S-succinyltransferase), a tricarboxylic acid (TCA) cycle enzyme, is an important mediator of MYC-driven leukemogenesis, and promotes tumor aggression in neuroblastoma." (PMID 38439957, 2024). "MYC is activated and dysregulated in a variety of childhood cancers, including neuroblastoma, Wilms tumor, ATRT, and medulloblastoma." (PMID 39766049, 2024). "We previously found that JMJD6 is essential for the survival of neuroblastoma cells (including MYCN-amplified and MYC-overexpressed cells), which was further validated by an independent study, indicating that neuroblastoma has JMJD6 dependency." (PMID 38488852, 2024). "In MYC-amplified neuroblastoma, hypoxic stress induces the expression of SHMT2, and knock-down of SHMT2 reduces tumorigenesis." (PMID 38331894, 2024). "Here, we demonstrate that jumonji domain containing 6, arginine demethylase, and lysine hydroxylase, JMJD6, acts as a hub connecting splicing and metabolism in MYC-driven human neuroblastoma." (PMID 38488852, 2024). "Dysregulated splicing as a vulnerability of MYC-driven cancers provides a rationale to target neuroblastoma by using splicing inhibitors as a therapeutic approach." (PMID 38488852, 2024). "MYCN is a member of the MYC proto-oncogene family, which also includes MYC and MYCL, and encodes a basic helix–loop–helix–leucine zipper (bHLH–LZ) TF, initially characterized in neuroblastoma." (PMID 37835497, 2023). "In these cancer models where MYC is amplified, which represent osteosarcoma and neuroblastoma, we and others have shown that MYC suppresses or interferes with BMAL1 and disrupts molecular clock oscillation." (PMID 37639465, 2023). "Here, we identified mitochondrial translation as a promising MYC-dependent target in multidrug-resistant neuroblastoma." (PMID 37973789, 2023). "For instance, glutamine starvation in MYC-mediated neuroblastoma has been shown to induce apoptosis through the GCN2-ATF4 branch." (PMID 37686063, 2023). "Turning to other cancers where BMAL1 is suppressed, MYC amplification in neuroblastoma alters BMAL1 mRNA expression through the induction of NR1D1." (PMID 37262074, 2023). "In this study, we utilize multiple cell line models representing neuroblastoma and osteosarcoma to determine the role of MYC overexpression in disruption of circadian oscillations of transcription and cell-autonomous metabolism." (PMID 37639465, 2023). "MYC-driven neuroblastoma mouse models typically exhibit incomplete penetrance and late onset, as only around 50% of the mice develop cancer within an average of 40 weeks." (PMID 37892172, 2023). "In line with the effects observed after DOXY treatment, chloramphenicol selectively inhibited mitochondrial translation and induced mitochondrial ISR leading to the downregulation of c-MYC in neuroblastoma cells." (PMID 37973789, 2023). "It should be emphasized that MYCN, a member of the MYC proto-oncogene family, is overexpressed in many types of cancer, including neuroblastoma, and is responsible for promoting proliferation and the survival of tumor cells." (PMID 38067269, 2023).
neuroblastoma (continued). "For example, in human neuroblastoma, MYC amplification distorts circadian repressors (NR1D1) and circadian activators (RORA and BMAL1) to cause metabolic rewiring that fuels cancer cell growth and promotes poor patient outcomes." (PMID 37262074, 2023). "It was discovered in 1983 as an amplified gene in neuroblastoma, a childhood tumor of the neural crest, with similarities to the c-MYC gene." (PMID 38001143, 2023). "Together, these results demonstrate mitochondrial ISR as the key pathway responsible for both downregulation of MYC proteins and induction of neuroblastoma cell death upon the mitoribosome inhibition." (PMID 37973789, 2023). "MYC, ALK, and Augα are all located on the 2p chromosome, and the exact 2p gain region is associated with the development of neuroblastoma." (PMID 37892172, 2023). "To functionally validate this MYC-dependent sensitivity, we utilized Tet21N neuroblastoma cells with tunable N-MYC expression (for details refer to Methods section)." (PMID 37973789, 2023). "Consistently, we provide evidence that MYC-driven neuroblastoma cells are particularly vulnerable to the ISR-mediated cell death, while p38 MAPK appears to further favor apoptosis induced by the mitochondrial ISR." (PMID 37973789, 2023). "Neuroblastoma is a typical MYC-driven cancer, and patients with neuroblastoma usually present with massive amplification of the N-MYC gene (MYCN), which leads to uncontrolled cancer cells." (PMID 36910646, 2023). "Germline PVs in MAX are associated with bilateral and multifocal PPGLs (67%) and the occurrence of both neuroblastomas and PPGLs, which highlights the importance of the MYC/MAX convergence point in these catecholamine-producing neoplasms." (PMID 37361539, 2023). "Malignant progression, therapy resistance and disease relapse in neuroblastoma are associated with an undifferentiated phenotype, which is linked to the broad activation/repression of MYCN/c-MYC target genes." (PMID 37361539, 2023). "The overexpression of c-MYC in neuroblastoma has been reported to block neuroblastoma differentiation and developmental arrest, thereby promoting the malignant phenotype of neuroblastoma." (PMID 37375824, 2023). "In a large tumor cohort of neuroblastoma, tumors with high mitotic gene expression were identified as being highly aggressive with expression of MYC target genes, likely stemming from MYCN amplification or high cMYC activity." (PMID 37958555, 2023). "The neuroblastoma MYC oncogene MYCN recruited HDAC2 to miR-183 promoter sequences to decrease the expression of miR-183 in neuroblastoma cells." (PMID 36968022, 2023). "The MYC family has three members: the most prominent c-MYC, MYCN, which was initially found to be associated with neuroblastoma, and MYCL associated with small cell lung cancer, hence the names." (PMID 37601651, 2023). "On the other hand, in B-ALL and neuroblastoma, MYC can cooperatively promote glutamine metabolism and lipogenesis with MondoA, and the overexpression of MondoA is associated with worse clinical outcomes." (PMID 37443779, 2023). "Yet, strategies targeting the MYC proteins for neuroblastoma treatment remain limited to preclinical studies." (PMID 37973789, 2023). "Our studies provide the first evidence that IGF2BP1 is a potent and druggable oncogene in neuroblastoma, with target prospects in other MYC/N-driven malignancies." (PMID 37246217, 2023). "The altered activity of the ALK receptor and increased expression of the downstream MYC transcription factor are the pivotal molecular hallmarks of neuroblastoma." (PMID 37765276, 2023). "In contrast to MYCN-overexpressing neuroblastoma, it is extremely rare to encounter gene amplification in the MYC-overexpressing neuroblastoma." (PMID 35053227, 2022). "MYCN, a MYC paralog, is frequently amplified in human neuroblastoma and was amplified in three human GCs in TCGA cohort." (PMID 34387762, 2022).
neuroblastoma (continued). "Taken together, these data suggest that EZH2 depletion induces MYC(N) degradation not only in neuroblastoma cells but also in other cancer cells overexpressing either the MYCN or MYC oncogene." (PMID 35013218, 2022). "The recent advance of neuroblastoma research with precision medicine approaches demonstrates that tumors in the UH group are also heterogeneous and four distinct subgroups—MYC, TERT, ALT and null—are identified." (PMID 35053227, 2022). "Targeting MYC-driven hypertrophic nucleoli: MYC-driven neuroblastomas characteristically show prominent nucleolar formation, a sign of increase in ribosome synthesis and translation." (PMID 35053227, 2022). "As MYC is a master driver of the oncogenic phenotype in neuroblastoma and acts as an amplifier of the expression of multiple downstream targets that promote proliferation, this is likely to underpin many of the phenotypic changes observed." (PMID 36263020, 2022). "In our study, we found eucalyptol can down-regulated MYC transcription in neuroblastoma SH-SY5Y cell." (PMID 36331666, 2022). "Tumors overexpressing MYC-family protein (MYCN overexpression detected in ~20% and MYC overexpression detected in ~10% of neuroblastomas of the undifferentiated and poorly differentiated subtypes) are collectively named MYC-driven neuroblastomas." (PMID 35053227, 2022). "MYCN-amplified neuroblastoma cells, like other MYC-driven cancer cells, have been found to be addicted to the amino acid glutamine (Gln), the absence of which causes growth arrest or apoptosis." (PMID 35484422, 2022). "Our findings identify cysteine uptake, transsulfuration and the lipid peroxidation-specific scavenging system as vulnerabilities in cancer cells driven by oncogenic MYC(N) activity such as MYCN-amplified neuroblastomas." (PMID 35484422, 2022). "The fact that the methyltransferase-inactive EZH2 is capable of modulating MYC(N) stability prompted us to examine its functional relevance in MYC(N)-driven neuroblastoma cells." (PMID 35013218, 2022). "MYC-driven tumors include large-cell neuroblastoma that is uniquely characterized by enlarged nuclei with one or a few very prominent nucleoli in relatively clear (euchromatic rich) background." (PMID 35053227, 2022). "ODC has been recognized as a potent oncogenic transforming factor, and in neuroblastoma, it is the most well-studied target of the transcription factor c-MYC/MYCN." (PMID 36551330, 2022). "Surprisingly, ASCL1 deletion had little effect on the transcription of CRC gene transcripts in these neuroblastoma cell lines, but the ability of MYC/MYCN and CRC component proteins, PHOX2B and GATA3, to bind to chromatin was compromised." (PMID 36263020, 2022). "The most highly mutated genes, such as MYC, TERT, FASLG, RIPK1, TNFSF10, TARDBP, and CDKN2A, have been well characterized in liver cancer, diffuse large B-cell lymphoma, neuroblastoma, and kidney renal clear cell carcinoma." (PMID 35875102, 2022). "A similar approach was employed for high-risk neuroblastoma, a cancer type characterized by genetic amplification and overexpression of n-MYC and, in some cases, of c-MYC oncogenes." (PMID 35565259, 2022). "MYCN amplification and MYC expression have been shown to correlate with a neuroblastoma tumor microenvironment low in infiltrating immune cells and low cellular immunity, suggesting its role in suppressing immunogenicity." (PMID 35326601, 2022). "Reduced binding of these factors is likely to contribute to the reduced proliferation of ASCL1 KO cells, particularly in the case of MYCN/MYC, whose role in driving proliferation in neuroblastoma is very well documented." (PMID 36263020, 2022). "These MYC-driven neuroblastomas are highly aggressive and histologically characterized by nucleolar hypertrophy (from one to a few prominent nucleolar formations) associated with higher levels of MYC-family protein expression." (PMID 35053227, 2022).
neuroblastoma (continued). "Neuroblastoma, a malignancy of arrested development of the peripheral nervous system, is a MYC-driven cancer." (PMID 34788094, 2021). "MYC and MYCN have been implicated in other pediatric tumors, including neuroblastoma and medulloblastoma, often in subsets of high-risk tumors." (PMID 34552068, 2021). "Together our results show that inhibition of fatty acid synthesis in neuroblastoma cells leads to reduced proliferation, increased cell death, lower levels of MYC(N) proteins, and induction of neural differentiation." (PMID 33659885, 2021). "MYC activation is the most frequent molecular alteration observed in human cancers, and among those, neuroblastoma represents a classic example." (PMID 34423893, 2021). "The EUH subset includes (i) MYC-driven neuroblastoma expressing high MYC and/or MYCN protein, (ii) Neuroblastoma with TERT overexpression due to genomic rearrangements, and (iii) Neuroblastoma of the ALT group due to ATRX loss." (PMID 33968044, 2021). "We next sought evidence that ALYREF mRNA expression in the organ of tumor origin, sympathetic ganglia, correlated with an MYC expression signature from tumor initiation to progression in tissues from the TH-MYCN+/+ transgenic neuroblastoma mouse model." (PMID 33767157, 2021). "EVs produced by MYCN-expressing cells or isolated from neuroblastoma patients induced the Warburg effect, proliferation and c-MYC expression in target cells." (PMID 34847775, 2021). "Previous studies have shown that concomitant inhibition of PI3K and BRD4 by SF2523 blocks MYC expression and activation, promotes MYC degradation, and markedly inhibits neuroblastoma cell growth and metastasis." (PMID 34926269, 2021). "We analysed EVs secreted from multiple neuroblastoma cell lines to confirm that glycolytic enzymes with oncogenic potential were enriched in MYC-expressing cells." (PMID 34847775, 2021). "Deregulated in over half of all human cancers and established as one of the prominent cancer stem cell markers in neuroblastoma, MYC oncoproteins represent an intriguing target for cancer therapy." (PMID 35008802, 2021). "Cyclin-dependent kinase 4 (CDK4) is one of the putative transcriptional targets of MYC and is highly expressed in neuroblastomas with MYCN amplification." (PMID 34069817, 2021). "Meanwhile, MYC has been found involved in the tumorigenesis or progression in neuroblastoma and genotype-C-HBV-related HCC via regulating the PPIA expression." (PMID 33790943, 2021). "Mechanistically, we linked the cancer-promoting activity of EVs to the glycolytic kinase pyruvate kinase M2 (PKM2) that was enriched in EVs secreted by MYC-expressing neuroblastoma cells." (PMID 34847775, 2021). "We found that MYCN levels and activity have a direct effect on fatty acid amount, as well as on glucose as the preferred carbon source for fatty acid synthesis in neuroblastoma, in agreement with our earlier results and studies in other MYC-driven tumors." (PMID 33659885, 2021). "Curcumin also inhibits transcriptional activation of the motility, angiogenesis, and metastasis-stimulating factor autotaxin (ENPP2) in human neuroblastomas where the MYC gene paralogue MYCN is amplified." (PMID 33937075, 2021). "Here, we show that neuroblastoma, a MYC-driven cancer characterized by splicing dysregulation and spliceosomal dependency, requires the splicing factor RBM39 for survival." (PMID 34788094, 2021). "Using five small molecule inhibitors targeting ACACA or FASN and siRNA targeting FASN, we show that inhibition of fatty acid synthesis decreases cell proliferation, reduces MYCN or c-MYC protein levels, and results in neural differentiation in neuroblastoma." (PMID 33659885, 2021). "This is because the PKM2 isoform is enriched in MYCN-amplified neuroblastoma cells due to the ability of the MYC transcription factors to transactivate the splicing factors PTBP1 and HNRNPA." (PMID 34847775, 2021).